NLRP3 (NLR family pyrin domain containing 3)
Diseases named in the same sentence as NLRP3 in open-access papers (continued):
Sharing a sentence is not in itself a finding about the gene and the disease.
Sepsis (continued). "This review builds upon prior work highlighting NLRP3 as a master regulator of inflammatory signaling in sepsis, while extending current understanding by addressing lesser-explored sensors like AIM2 and IFI16." (PMID 40558557, 2025). "To assess the translational relevance of these findings, we employed a murine sepsis model, induced by LPS-triggered NLRP3 inflammasome activation." (PMID 40520006, 2025). "Further, it emphasized the central role of NF-κB/NLRP3 signaling pathway is in sepsis and how IL-1R2-mediated inhibition of this axis leads to the decrease in recruitment and activation of effector cells of immune system." (PMID 40699828, 2025). "The NLRP3 inflammasome activation is a tightly controlled process that regulates the release of the powerful pro-inflammatory cytokine IL-1β in sepsis." (PMID 40086696, 2025). "In alveolar macrophages, extracellular histone-mediated TWIK2 upregulation triggers K+ efflux and activates the NLRP3 inflammasome, thereby resulting in excessive lung inflammation during sepsis." (PMID 40307577, 2025). "The preclinical studies in neonatal models exploring the role of aluminum-based adjuvants (alum) have revealed that the prophylactic activation of the NLRP3 inflammasome augments innate immune responses and increases survival in neonatal sepsis models." (PMID 41149694, 2025). "Overactivation of and disproportionate responses to NLRP3 are involved in the development of numerous conditions, including kidney disease and sepsis-induced AKI." (PMID 40869248, 2025). "In sepsis, accumulated bile acids act as DAMPs to activate the NLRP3 inflammasome-IL-1β axis, accompanied by the down-regulation of the FXR, forming a “cholestasis-inflammation-organ injury” vicious cycle." (PMID 41244772, 2025). "Further investigations have revealed that during sepsis, macrophage autophagy hinders the activation of the NLRP3 inflammasome by targeting the lysosome responsible for degrading IL-1β, thereby diminishing the secretion of IL-1β." (PMID 40918153, 2025). "In myocardial tissues and cardiomyocytes, miR-96-5p targets NLRP3 to regulate sepsis-induced myocardial injury." (PMID 40307577, 2025). "Our study found that Mdivi‐1 alleviated sepsis‐induced microglia NLRP3 through enhancing p62 level, which mediating autophagosome formation." (PMID 39791542, 2025). "In summary, our findings indicate that ET enhances autophagic flux, suppresses NLRP3 inflammasome activation, and mitigates excessive inflammatory responses in sepsis." (PMID 40918153, 2025). "For instance, microglial NLRP3 activation in PD displays distinct regulatory patterns compared to macrophage responses in sepsis, while epithelial responses to viral infections diverge from those of myeloid cells." (PMID 40959087, 2025). "In the context of sepsis and acute kidney injury, the most extensively studied inflammatory vesicle is NLRP3, which is activated in response to stimulation by PAMPs and DAMPs." (PMID 40657645, 2025). "In sepsis-associated liver injury, GBP5 activates the NLR family pyrin domain containing 3 (NLRP3) inflammasome, exacerbating inflammation and tissue damage." (PMID 40788157, 2025). "SOX9 inhibits the expression of miR-96-5p by binding to its promoter region and then promotes the expression of NLRP3, exacerbating the myocardial injury and pyroptosis of cardiomyocytes induced by sepsis." (PMID 40643532, 2025). "Recently, with respect to the pathogenesis of sepsis, the activation of the Nod-Like Receptor Family Pyrin Domain Containing 3 (NLRP3) inflammasome to induce pyroptosis in AMs has been identified as a causative factor." (PMID 40599023, 2025). "For instance, phillyrin prevented sepsis-induced acute lung injury through inhibiting the NLRP3/caspase-1/GSDMD-dependent pyroptosis signaling pathway." (PMID 40708650, 2025).
Sepsis (continued). "In parallel to TLR4, the NLRP3 inflammasome—a pattern recognition receptor involved in innate immune responses—also plays a central role in inflammation and tissue injury in sepsis-induced AKI." (PMID 40869248, 2025). "Our findings reveal a new role for ATG16L1 in regulating macrophage NLRP3 feedback activation during sepsis, suggesting it as a potential therapeutic target for treating sepsis‐induced ALI." (PMID 40211890, 2025). "HMGB1 also plays a crucial role in aseptic inflammation by activating the NLRP3 inflammasome, inducing IL-1β secretion and sepsis, and recruiting neutrophils and eosinophils, resulting in inflammatory infiltration and tissue damage." (PMID 40688353, 2025). "Several studies have established the involvement of the cGAS-STING-NLRP3 axis in NLRP3 inflammasome activation during sepsis, with implications in cardiac, pulmonary, and renal injury associated with the condition." (PMID 41327452, 2025). "In summary, these studies highlight the potential of polymer‐based nanocarriers in targeting inflammation through ROS scavenging and NLRP3 inflammasome inhibition in sepsis and related injuries." (PMID 40599085, 2025). "It has been demonstrated that Heat Shock Factor 1 (HSF1) mitigates sepsis-induced lung injury through the promotion of NLRP3 ubiquitination in macrophages." (PMID 40028334, 2025). "Huanget al. reported that HMGB1-induced NLRP3 inflammasome activation contributes to the development of acute lung injury in sepsis-induced models." (PMID 40599023, 2025). "These bioinformatics analyses are almost consistent with the results obtained from our molecular biology techniques, suggesting that inhibiting the activation and pan apoptotic process of NLRP3 inflammasome is the key to ECG improving sepsis induced ALI." (PMID 41496909, 2025). "Summary of studies done so far on nanosized drug delivery systems targeting NLRP3 inflammasome for enhancing the treatment of sepsis." (PMID 40599085, 2025). "To validate the physiological relevance of our in vitro observations, we employed a well-established murine model of LPS-induced sepsis, which is driven by NLRP3 inflammasome-mediated inflammatory responses." (PMID 40520006, 2025). "Inhibition of the NLRP3 inflammasome and its products has also been proposed as a therapeutic target in the treatment of acute renal failure, including sepsis-induced AKI." (PMID 40869248, 2025). "Together, these in vivo findings establish that emodin confers protection against LPS-induced sepsis primarily by suppressing NLRP3 inflammasome activation, thereby dampening downstream inflammatory responses." (PMID 40520006, 2025). "To explore the mechanisms involved, we focused on the recently identified PLK1/AMPK/DRP1 signaling axis, which has been shown to inhibit ROS-mediated NLRP3 inflammasome activation and attenuate sepsis-induced acute lung injury." (PMID 40918153, 2025). "Our previous study indicated that sepsis activates the mitochondria-dependent NLRP3 inflammasome pathway and increases the release of inflammatory cytokines such as IL-1β." (PMID 40575778, 2025). "It has been shown that the NLRP3 pathway is involved in sepsis and that its inhibition leads to improvement of muscle atrophy and inflammation." (PMID 41315622, 2025). "Experimental models demonstrate that NLRP3 inhibition significantly attenuates LPS-induced acute lung injury and improves sepsis-related inflammatory responses and organ damage." (PMID 41256846, 2025). "Compounds such as baicalin, cortistatin, and sulfur dioxide have been reported to inhibit NLRP3 activation, reduce IL-1β and IL-18 levels, and mitigate oxidative stress and cell death in animal models of sepsis." (PMID 40558557, 2025). "In the same regard, the inhibitory role of Hsp70 in NLRP3 regulation has been reported in acute kidney injury models, sepsis-induced cardiomyopathy, and microglia pyroptosis-induced post-operative cognitive dysfunction." (PMID 40319428, 2025).
Sepsis (continued). "As an antidiabetic drug, Biguanide (BF) upregulates autophagy and Nrf2 protein levels through an AMPK-dependent pathway, thereby inhibiting NLRP3-mediated pyroptosis in sepsis-induced ALI." (PMID 40766066, 2025). "STING signaling promoted the p-IRF3 nuclear translocation, NLRP3 inflammasome priming, and transient DC pyroptosis, thereby exacerbating hyperinflammation in the acute phase of sepsis." (PMID 41647935, 2025). "In sepsis, overexpressed YTHDF1 inhibits CLP‐induced inflammation in mice by upregulating E1 Ub protein ligase 1 to promote NLRP3 ubiquitination and inhibit caspase 1‐dependent pyroptosis, thereby alleviating sepsis." (PMID 40919129, 2025). "NLRP3 inflammasome activation has been reported to play a beneficial role in burn wound healing, burn sepsis, burn-induced ALI, and hypertrophic scarring." (PMID 40625798, 2025). "In summary, this study revealed that ATG16L1 regulates macrophage NLRP3 activation during sepsis and interacts with alveolar epithelial cells to form a positive feedback activation loop during sepsis‐induced lung injury." (PMID 40211890, 2025). "Accumulating data suggest that the NLRP3 inflammasome plays a key role in the pathogenesis of sepsis." (PMID 39887250, 2025). "The NLRP3 inflammasome serves as a critical signaling hub in sepsis by integrating diverse endogenous and exogenous stress signals." (PMID 40558557, 2025). "Zn2+ upregulated Parkin acetylation by repressing sirtuin 7 activity to promote mitophagy and inhibit NLRP3 inflammasome activation and pyroptosis, thus improving sepsis-induced acute kidney injury." (PMID 40989844, 2025). "The authors suggested an important role for the miR-20a-5p/NLRP3 pathway in the development of sepsis in patients with acute kidney injury." (PMID 40004454, 2025). "Inflammasome activation in sepsis, particularly through the NLRP3 complex, directly induces pyroptosis through GSDMD cleavage by caspase-11 in murine models, or caspase-4/5 in humans in response to cytosolic LPS." (PMID 40959087, 2025). "Inflammasomes play a key role in the inflammatory response of sepsis and the NLRP3 inflammasome is one of the most widely studied types." (PMID 40643532, 2025). "Recent studies have shown that the protein ubiquitination system is involved in regulating the activation process of the NLRP3 inflammasome, and this mechanism is of great significance for the development of sepsis." (PMID 40643532, 2025). "Expression of miR-20a-5p was significantly reduced in a mouse model of sepsis, and miR-20a-5p was shown to regulate NLRP3 activity while blocking miR-20a-5p-enhanced LPS-induced cellular pyroptosis." (PMID 40004454, 2025). "Collectively, these studies highlight the potential of inorganic nanocarriers in targeting the NLRP3 inflammasome and offering cardioprotective effects in sepsis‐induced myocardial injury." (PMID 40599085, 2025). "In summary, ECG exerts an ameliorative effect on sepsis-induced ALI by inhibiting the NLRP3/Caspase-1/GSDMD signaling pathway." (PMID 41496909, 2025). "By regulating the key molecule GSDMD, pyroptosis activates the NLRP3 inflammasome and caspase-1-dependent apoptosis, contributing to myocardial dysfunction in sepsis." (PMID 40526611, 2025). "In line with findings for TLR4, MyD88, and NF-κB, sepsis significantly increased renal expression of NLRP3 and caspase-1 and its activated form (cleaved caspase-1 protein) compared to controls, as shown through Western blotting." (PMID 40869248, 2025). "Specifically, the NLRP3 inflammasome has been recognized as a central component of innate immunity and the pathophysiology of sepsis." (PMID 40959087, 2025). "The replenishment of NAD+ pool promoted the recovery of mitochondrial function and further alleviated NLRP3 inflammasome-mediated sepsis by ROS elimination." (PMID 40809343, 2025). "Collectively, these results indicate that BA suppresses the NLRP3 inflammasome activation in sepsis." (PMID 39887250, 2025).
Sepsis (continued). "In our model, CLP-induced sepsis increased the renal expression of NLRP3, caspase-1 in its mature and activated form, and IL-1β, consistent with previous reports." (PMID 40869248, 2025). "Recent research has shown that rhodopsin offers a protective effect on the heart, confirming that the activation of NLRP3 inflammatory vesicles contributes to cardiomyocyte death during sepsis." (PMID 40458798, 2025). "This genetic specificity highlights that emodin's beneficial effects in LPS-induced sepsis are fundamentally reliant on NLRP3 inflammasome activation." (PMID 40520006, 2025). "Activation of caspase 1 (CSP-1) by the NLRP3 inflammasome during sepsis leads to pyroptosis and massive release of high-mobility group box protein (HMGB1), which is one of the lethal mechanisms of sepsis." (PMID 41315622, 2025). "NLRP3, a member of NOD-like receptor (NLR) family, is a type of PRRs found in cytoplasma that forms the NLRP3 inflammasome, a key complex sepsis development." (PMID 40461967, 2025). "The positive feedback activation of NLRP3 triggers an uncontrollable inflammatory response, thereby exacerbating sepsis‐induced ALI." (PMID 40211890, 2025). "Numerous investigations have demonstrated the role of NF-κB in NLRP-3 activation during sepsis that aggravates the inflammatory reaction toward septic shock." (PMID 40770673, 2025). "Polymer‐based nanocarriers that respond to oxidative stress by scavenging ROS and inhibiting the NLRP3 inflammasome have been widely developed for treating conditions characterized by oxidative stress and inflammation, such as sepsis‐related ALI." (PMID 40599085, 2025). "Seven components of YNJ were identified as potential regulators of the NF-κB/NLRP3 pathway, with three among those promoting, under sepsis-mimicking conditions, lung alveolar epithelial cell survival and M2 polarization of macrophages." (PMID 39925847, 2025). "Reactive oxygen species (ROS) produced during sepsis can act as a second signal to stimulate the activation of the NLRP3 inflammasome." (PMID 40766788, 2025). "NanoFe○Decreased levels of NLRP3 inflammasome markers.○Protected against myocardial injury in sepsis via attenuation of inflammation." (PMID 40599085, 2025). "Among them, the NLRP3 inflammasome stands out as a molecular hub that integrates diverse danger signals and orchestrates the inflammatory cascade in sepsis." (PMID 40558557, 2025). "This nanosystem showed potential in downregulating the levels of inflammasome components such as NLRP3, caspase‐1, and IL‐1β, suggesting its ability to modulate inflammasome activation in sepsis‐induced lung injury." (PMID 40599085, 2025). "It has been established through a series of studies that pyroptosis, which is mediated by the NLRP3 inflammasome, plays a crucial role in the pathophysiology of sepsis." (PMID 40708650, 2025). "In sepsis‐associated liver injury, GBP5 overexpression aggravates liver damage by promoting the release of inflammatory cytokines through NLRP3 inflammasome activation." (PMID 40636987, 2025). "In the models of LPS-induced sepsis, melatonin inhibits NLRP3-GSDMD pathway via activating Nrf2/HO-1 signaling axis to reduce ALI/ARDS in vivo and in vitro." (PMID 40028334, 2025). "Cilastatin was originally developed to inhibit the renal metabolism of imipenem by DHP-I, and it is not a known anti-inflammatory agent or direct ligand of TLR4 or NLRP3, although it protects against sepsis-induced AKI by decreasing inflammation." (PMID 40869248, 2025). "The NLRP3 inflammasome, upregulated in sepsis, triggers the release of IL-1β, dependent on cell pH and facilitated by aquaporin-mediated water influx in macrophages." (PMID 39544938, 2024). "We have shown that sepsis in mice activates the NLRP3 inflammasome, leading to the release of IL-1β, IL-6, and other cytokines and chemokines, causing cardiomyocyte (CM) dysfunction." (PMID 39201339, 2024).
Sepsis (continued). "The results showed that sepsis significantly promoted NLRP3, Pro Caspase-1, ASC and IL-18 mRNA levels, increased NLRP3, Pro Caspase-1, Cleaved Caspase-1 and ASC protein expression, whereas pretreatment with 6 and 30 mg/kg taraxerone attenuated these effects." (PMID 39543653, 2024). "Simultaneously, taraxerone disrupted the NLRP3 inflammasome signaling pathway, thereby alleviating M1 polarization of macrophages and mitigating sepsis-induced pulmonary inflammation and oxidative stress." (PMID 39543653, 2024). "Intriguingly, the deletion of Nlrp3 alleviated endotoxin-induced coagulation, supporting that NLRP3 inflammasome is at least one of the major mechanisms of sepsis-induced DIC." (PMID 38789414, 2024). "Observations of Nlrp3hi AMs and IMs secreting proinflammatory cytokines, characteristic of classically activated (M1) macrophages, prompted us to explore the role of NLRP3 in myeloid cell differentiation after sepsis." (PMID 39405117, 2024). "In the context of sepsis-induced skeletal muscle atrophy, the use of NLRP3 inhibitors has shown promising effects in alleviating the condition by inhibiting catabolic processes and cachexia-associated inflammation." (PMID 38338718, 2024). "The mice were subjected to a two-hit model of 25–30% TBSA scald burn, followed by Pseudomonas aeruginosa wound infection 72 h after burn, to further explore the roles and mechanisms of the NLRP3 inflammasome in burn sepsis." (PMID 38957662, 2024). "MINK1 also takes part in NLRP3 inflammasome activation, which suggests its role in related diseases, such as type 2 diabetes, gout, and sepsis." (PMID 39727954, 2024). "In this study we show that CLP-sepsis increased the serum levels of the cytokine IL-1β, which is secondary (at least in part) to the activation of NLRP3 inflammasome during sepsis." (PMID 39559354, 2024). "Recent investigations have indicated that formononetin mitigates sepsis-induced organ damage by activating the hnRNPUL2/NLRP3 and PI3K/AKT pathways." (PMID 39549609, 2024). "This study unveils the PADIs/NLRP3/Ym1 pathway as a potential target in treatment of sepsis-induced ALI." (PMID 39405117, 2024). "In the cecal-ligation puncture rat model of sepsis, MCC950 is another NLRP3 inhibitor, attenuates NLRP3 activation in platelets and decrease the levels of NLRP3 inflammasome associated cytokines." (PMID 39736771, 2024). "The transcription factor USF2 activates TSP-1 to activate the TGF-β/NLRP3/Caspase-1 signaling pathway, resulting in promotion of the oxidative stress response and stimulation of pyroptosis in sepsis-induced AKI." (PMID 38516004, 2024). "The results showed that the mRNA levels of NLRP3 and IL‐18 were significantly increased in sepsis patients compared with healthy controls." (PMID 39692606, 2024). "This study is the first to focus on the role of HSPA8 in regulating NLRP3 inflammasome activation in AECs in the development of sepsis-induced lung injury." (PMID 38698431, 2024). "Toxoplasma gondii dense granule protein (TgGRA9) regulates NLRP3 inflammasome activation to treat host sepsis and interacts with NLRP3, inhibiting the formation of the NLRP3 inflammasome by preventing the binding of ASC to NLRP3 in mitochondria." (PMID 39548522, 2024). "It comprises NLRP3, which detects danger and recruits molecules; caspase-1, essential for cytokine maturation and processing gasdermin D for cytokine release and sepsis; and ASC, bridging NLRP3 and caspase-1." (PMID 38922058, 2024). "In a model of sepsis induced by LPS/ATP, activation of NLRP3 inflammasome hinges on heightened glycolysis and increased mitochondrial antiviral signalling protein expression." (PMID 39623879, 2024). "For instance, serine-arginine protein kinase 1 (SRPK1) can inhibit sepsis-induced acute lung injury (ALI) by modulating the PI3K/AKT/ forkhead box O 3/NLRP3 pathway." (PMID 38716051, 2024). "IMD1 − 53 provide protection against heart injury and inflammation by attenuating the NLRP3/Caspase-1/IL-1β pathway during sepsis." (PMID 38616256, 2024).